EIF4E (eukaryotic translation initiation factor 4E)
Diseases named in the same sentence as EIF4E in open-access papers (continued):
Sharing a sentence is not in itself a finding about the gene and the disease.
tumor (continued). "In hepatocellular carcinoma, tumor cell-intrinsic PD-1 can active mTOR pathway, which binds to the downstream target molecules S6 and eIF4E and promotes their phosphorylation, thus promoting tumor progression independently from specific immunity." (PMID 34326692, 2021). "In xenograft mouse models, elevated eIF4E correlates with increased tumor numbers, invasion, and metastases, while pharmacological inhibition or reduction of eIF4E levels suppress tumor growth." (PMID 34944805, 2021). "In our previous work, we have shown that phenazine derivative phenazine #14 specifically disrupted the Hsp27/eIF4E interaction, increased apoptosis, and decreased tumor growth." (PMID 33925528, 2021). "A clinical trial of the ASO LY2275796 in patients with solid tumors, while failing to observe a tumor response, found tumor eIF4E levels to be generally reduced at the protein and mRNA levels." (PMID 34639005, 2021). "We further explored the relationship between eIF4E and tumor infiltrating immune cells using ImmuCellAI and the TIMER database." (PMID 34876062, 2021). "Preclinical studies using ASOs have shown reductions in eIF4E levels accompanied by slowing of tumor proliferation in vitro and in vivo." (PMID 34639005, 2021). "eIF3C, eIF3D and eIF4E even correlated with tumor grade as their expression was significantly higher in HGG than in LGG." (PMID 33807050, 2021). "Analysis of the samples obtained showed a reduction in eIF4E:eIF4G1 interaction among tumours treated with SBI-756 as a single agent or in combination with venetoclax, compared to vehicle or venetoclax alone." (PMID 33318657, 2021). "Next, we used the PrognoScan database to explore the relationship between the expression of eIF4E and the prognosis of tumor patients." (PMID 34876062, 2021). "Our work found that the expression of mutant Kras in tumor models of the mouse intestinal epithelium increased the phosphorylation of eIF4E (eukaryotic translation initiation factor 4E), the mRNA cap-binding protein." (PMID 33855169, 2021). "This is mediated, in part, through hyperphosphorylation of the oncogene eIF4E, since genetic perturbation of this posttranslational modification delays tumor initiation and progression, and improves overall survival." (PMID 34032633, 2021). "We further used the GEPIA database to evaluate the relationship between the expression of eIF4E and the prognosis of patients and analyzed 33 tumor types." (PMID 34876062, 2021). "The significant overexpression of eIF4AI (p < 0.001) and eIF4E (p < 0.001) was seen in tumor tissue compared to NNT." (PMID 33540613, 2021). "Previous studies have confirmed that eIF4E was overexpressed in multiple tumor tissues including breast, lung, head, and neck tumors." (PMID 33489719, 2020). "It is thought that eIF4E-sensitive mRNAs which are characterized by the long, complex and highly structured 5’-UTR mainly encoding proliferation and tumor-promoting proteins such as Bcl-xL, C-myc, Cyclins and vascular endothelial growth factor (VEGF)." (PMID 33148274, 2020). "Complementing the results observed in the phospho-eIF4E deficient mice, pharmacological inhibition of MNK1/2 using the less selective inhibitor merestinib, in tumor bearing mice, decreased the levels of neutrophils in the lung." (PMID 32517051, 2020). "The aberrant overexpression of key proteins via cap-dependent mRNA translation is known to be a requisite for tumor progression and metastasis via the strong activation of the eukaryotic initiation factor (eIF) 4E-binding protein 1 (4EBP1/eIF4E) axis in RCC." (PMID 32252440, 2020). "The other two target genes, SSR1 and EIF4E, were upregulated through downregulation of miR-483-5p (which plays a tumor promoter or tumor suppressor role, based on cellular context)." (PMID 32204397, 2020).
tumor (continued). "The results of second-generation ASOs targeting eIF4E are encouraging, these ASOs effectively suppressed eIF4E expression in tumors, and greatly attenuate tumor burden in breast and prostate xenograft models." (PMID 33148274, 2020). "4EBP1 suppresses cellular proliferation by inhibiting eIF4E-mediated protein synthesis, suggesting that 4EBPs function as tumor suppressors." (PMID 32075852, 2020). "eIF4E phosphorylation was suggested to be an important event in tumorigenesis and tumor progression." (PMID 33148274, 2020). "As described in Section 4.2., eIF4E is deregulated in a vast majority of tumor entities including CRC." (PMID 32455578, 2020). "Mnk-mediated eIF4E phosphorylation favors the mRNA translation of proteins involved in tumor cell proliferation and survival." (PMID 32708122, 2020). "Recent work by the Sonenberg lab demonstrates that eIF4E activity promotes the survival of pro-metastatic neutrophils and contributes to tumor metastasis." (PMID 32731503, 2020). "eIF4E overexpression leads to tumor formation in mouse models and to oncogenic transformation in immortalized cell lines." (PMID 33375634, 2020). "In xenograft mouse models, elevated eIF4E correlates with increased tumor numbers, invasion, and metastases." (PMID 33375634, 2020). "siRNAs against eIF4E can inhibit tumor growth and stimulate the cytotoxic effects of cisplatin in human breast cancer in vitro and in vivo." (PMID 32967226, 2020). "The role of eIF4E phosphorylation is not completely understood, but it seems to be essential for the tumor-promoting functions of eIF4E." (PMID 32455578, 2020). "Pro-metastatic neutrophils isolated from eIF4ES209A/S209A-bearing mice also manifest a decreased protein expression of anti-apoptotic factors BCL2 and MCL1, implicating the role of phospho-eIF4E in creating an anti-tumor microenvironment." (PMID 32517051, 2020). "EIF4E3 is downregulated in rapidly proliferating tumor cells, whereas EIF4E1 (formerly known as EIF4E) is abundantly expressed in tumor cells, although it is also present in most cells and plays an important role in angiogenesis." (PMID 32953883, 2020). "The over-expression and activation of eIF4E are connected with tumor formation, metastasis and increased tumor invasion." (PMID 32708122, 2020). "Previous study has shown that mTOR and eIF4E are two major proto-oncogenes related to oncogenic transformation, which are involved in tumor growth and development." (PMID 32023262, 2020). "Significant correlations between p-eIF4E expression and poor prognosis have been reported on various tumours." (PMID 31258849, 2019). "eIF4E phosphorylation promotes tumor development in prostate and has been found to be elevated in PCa." (PMID 30761182, 2019). "The ratio between phospho-S65 eIF4E-BP and its total amount was also similar in both tissue types, although the amount of both phospho-S65 and total eIF4E-BP was higher in tumor tissues." (PMID 31354733, 2019). "All these effects were effectively blocked by EIF4E-siRNA, confirming the essential role of eIF4E in PSC-tumour communication." (PMID 30923340, 2019). "If so, the effect of conditioning the growth medium of tumour cells with the secretome of activated PSCs should be suppressed by inhibiting eIF4E expression." (PMID 30923340, 2019). "A broad range of translation initiation factors are also commonly found to be either amplified or mis-regulated in tumours, including eIF4E (elongation initiation factor 4E)." (PMID 31118010, 2019). "Next, we explored the effect of vanillic acid on the Raf/MEK/ERK pathway that directly phosphorylates eIF4E and plays a pivotal role in tumor cell survival and proliferation." (PMID 30678221, 2019). "Several in vitro and in vivo studies have clearly shown that the Mnk-eIF4E axis promotes BC transformation and tumor progression, findings that are also supported by clinical data." (PMID 30832411, 2019).
tumor (continued). "A study demonstrated that EIF4E3 relies on cap-binding activity to act as a tumor suppressor and compete with the growth-promoting functions of EIF4E." (PMID 30881302, 2019). "Recent studies have demonstrated that progression and resistance to standard therapies in tumour is closely related to the eIF4E pathway." (PMID 30923340, 2019). "Inhibiting the interactions of PHGDH/eIF4A1 and PHGDH/eIF4E will provide potential targets for anti-tumor therapeutics development." (PMID 30744688, 2019). "Many cellular proteins that exhibited variations were found to be under the regulatory control of eukaryotic translation initiation factor 4E (eIF4E), whose expression was triggered in tumour cells grown in the secretome of activated PSCs." (PMID 30923340, 2019). "In tumours, elevated eIF4E function selectively and disproportionately increases translation of weak mRNAs." (PMID 30677218, 2019). "The activity of mTOR was not upregulated, although basal levels of the mTOR substrate (eIF4E-BP) were significantly higher in tumor cells." (PMID 31354733, 2019). "We propose that VNLG-152R can inhibit tumor cell metastasis chiefly/partly via promoting Mnk1/2 degradation thereby hampering oncogenic eIF4E signaling." (PMID 30832411, 2019). "In this study, SRO-91 effects are similar to those obtained with RBV, which coincides with its role on many genes involved in regulation of expression of proteins with important functions in tumor progression, notably inhibition of one of them, i.e. eIF4E." (PMID 31825993, 2019). "In our analysis, we confirmed that eIF4E acts as a key signalling molecule that mediates crosstalk between PSCs and tumour cells." (PMID 30923340, 2019). "This potential role of eIF4E proteins in tumor biology is also supported by studies confirming that eIF4E is involved in cell proliferation and tumor growth." (PMID 31795417, 2019). "We used multivariate analysis to investigate the association between recurrence-free survival and expression levels of p-eIF4E, eIF4E, and p-4EBP-1 in the patients with tumor recurrence." (PMID 31756179, 2019). "In contradistinction, the syntheses of a subset of pro-tumor factors are sensitive to eIF4E phosphorylation." (PMID 30804329, 2019). "Dysregulated mRNA translation occurs frequently in tumours due to elevated eIF4E expression or a hyperactive mTOR complex 1 (mTORC1) signaling pathway that results in the inactivation of the eIF4E binding proteins (4E-BPs)." (PMID 30138450, 2018). "As expected, phosphorylation and levels of eIF4E increased significantly in the tumor samples (about 1.5 and 2.6-fold respectively), what is in agreement with the results shown by other authors." (PMID 29568373, 2018). "The role of the protein synthesis initiation factor, eIF4E, has been studied in detail in tumor cells." (PMID 30286779, 2018). "Evidence indicates that the disruption of protein synthesis at the level of 4EBP1/eIF4E downstream of mTORC1 stimulates tumor formation." (PMID 29416809, 2018). "The eIF4E/4E-BP1 ratio is a key determinant of cell response to mTOR inhibitors as tumour cells with a high eIF4E/4E-BP1 ratio exhibit low sensitivity to asTORi-induced cell proliferation arrest." (PMID 30138450, 2018). "Both eIF4E and 4E-BP1 and their relative abundance have been linked to tumour progression and mTOR kinase resistance." (PMID 29389967, 2018). "According to these results, we believe that up-regulation of MNK2 promotes tumor proliferation and metastasis via phosphorylated eIF4E in NSCLC, leading to poorer prognosis, later clinical stage, and higher chance of lymph node metastasis." (PMID 28878291, 2017). "Immunohistochemistry analysis revealed a significant reduction in phospho-S6 and eIF4E levels in tumor-bearing radioresistant OML1-R mice treated with BEZ235 compared with that by either IR or control treatments." (PMID 28978144, 2017).
tumor (continued). "The eIF4E3 binds m7GTP in an atypical manner, marginally suppresses eIF4E-dependent translation in diffuse large B-cell lymphoma, and is a tumor suppressor." (PMID 29317983, 2017). "Perhaps during gradual tumor hypoxification, there is selective pressure on hypoxic cells to repress eIF4E-dependent translation early and activate eIF4E2 early." (PMID 29317983, 2017). "Targeting eIF4E2 relative to eIF4E has the potential to be more selective for malignant cells (hypoxic tumor cells) subsequently leading to lower toxicity." (PMID 29317983, 2017). "For example, tumor localization to the frontal lobes was positively correlated with abundance of MYH11, and was negatively associated with eIF4E expression." (PMID 28781988, 2017). "In summary, to the best of our knowledge the data presented herein is the first report linking EPO-mediated tumor proliferation to eIF4E activation." (PMID 28415825, 2017). "Patient tumor samples in our study clearly exhibit a continuum of eIF4E/4E-BP1 ratios, and tumors with high eIF4E/4E-BP1 tend to be poorly differentiated and associated with lower overall survival." (PMID 28881582, 2017). "We performed our screening using phenazine derivatives that were previously shown to have an anti-tumor activity in pancreatic and prostatic cell lines and structure similar to inhibitors of the eIF4E/eIF4G interaction." (PMID 29100389, 2017). "MAPK-interacting kinase (MNK) can directly regulate eIF4E phosphorylation in response to a variety of signals affecting tumor cell growth." (PMID 27926520, 2017). "It was indicated in NSCLC that eIF4E is phosphorylated by MNKs, where overexpression of phosphorylated eIF4E predicts poor survival and correlates with tumor progression." (PMID 28878291, 2017). "Our patient's tumor demonstrated overexpression of EIF4E, an oncogene and downstream molecule of mTOR." (PMID 28993730, 2017). "Meanwhile, EIF4E can be directly targeted by the tumor suppressor miR-34c-3p and knock-down of EIF4E inhibits NSCLC cell proliferation." (PMID 28903455, 2017). "4E-BP1 and eIF4E have been shown to be critical in the tumor generation driven by the Akt and N-Ras oncogenes in the genetic mouse model of HCC." (PMID 28881582, 2017). "The aberrant increase of eIF4E activity results in the tumor initiation, development and metastasis through promoting the translation and expression of many oncogenes." (PMID 27907907, 2016). "Concurrently, repression of eIF4E contributed to boost the tumor growth inhibition of DDP, and tumors with eIF4E knockdown were much more sensitive to DDP than the blank control group (P = 0.0187)." (PMID 27588477, 2016). "In contrast, knockdown of eIF4E expression showed a significant delay for tumorigenicity, as well as decrease in tumor size and tumor weight compared to the mice with control or overexpressed eIF4E." (PMID 27588477, 2016). "Plenty of studies have discovered the resistance to cisplatin in tumor cells both in vitro and in vivo, but the literature regarding eIF4E and ESCC chemosensitivity is scant." (PMID 27588477, 2016). "Phosphorylation of eIF4E increases in the initial stages of the development of tumors of the breast, colon, stomach, and lung." (PMID 27440383, 2016). "Over-expression of eIF4E is one of the early events in breast tumorigenesis, and is sufficient to induce transformation of cells in mouse tumor models." (PMID 27276678, 2016). "Increasing evidences implicate the Mnks and/or Mnk-dependent phosphorylation of eIF4E play important roles in cell transformation, tumorigenesis or tumor progression." (PMID 27050281, 2016). "According to IHC analysis, eIF4E protein expressed extensively in tumor tissues (81.11%, 73/90), while only 22.22% (20/90) in ANCTs and 16.67% (6/36) in normal esophageal tissues (Control group)." (PMID 27588477, 2016). "The eIF4E/eIF4G interaction is highly regulated by competitive binding of 4EBPs, which are at a convergence point of signaling pathways and act as tumor suppressors." (PMID 27668427, 2016).
tumor (continued). "Our results demonstrated that inhibition of eIF4E expression resulted in an augmented cell viability inhibition in vitro and a significant tumor reduction and synergistic effects with cisplatin in a xenograft model." (PMID 27588477, 2016). "Ascitic fluid injection (A group) mimicked the indirect effects of tumour growth, including reductions in the expression of eIF4E and 4EBP1 (the ascitic fluid accounted for significant effects at P = 0.0504 and P = 0.0144, respectively)." (PMID 26847205, 2016). "The eIF4E inhibitor ribavirin has been shown to block the eIF4E-dependent export and translation of mRNA and to suppress tumor growth in a mouse xenograft model." (PMID 27462781, 2016). "Similar to the effects we observed in vitro, tumor growth decreased dramatically in eIF4E-shRNA group with DDP treated." (PMID 27588477, 2016). "But the significance of apoptosis induction and radiosensitivity on the anti-tumor activities of eIF4E/eIF4G interaction inhibitor remains undefined in NPC." (PMID 26942880, 2016). "Previous studies have shown that ribavirin has antitumor activity in various tumor cells in an eIF4E-dependent manner." (PMID 26317515, 2015). "One of the mechanisms of resistance of tumor cells to drugs targeting the mTORC1 can be based on the sustained activity of mTORC1-4EBP1/eIF4E pathway." (PMID 26636543, 2015). "Phosphorylation of eIF4E Ser-209 by Mnk1/2 is known to affect cell proliferation and tumor malignancy." (PMID 25923732, 2015). "The eukaryotic translation initiation factor 4E (eIF4E), which is the main composition factor of eIF4F translation initiation complex, influences the growth of tumor through modulating cap-dependent protein translation." (PMID 26317515, 2015). "In this study, we demonstrate that it is possible to directly target p-eIF4E, an unrealized attractive target for anti-tumor intervention, using small molecules." (PMID 25915158, 2015). "Phosphorylation of eIF4E at Ser-209 by the kinases Mnk1 and Mnk2 in response to mitogens, tumor promoters, and growth factors is critical for its oncogenic activity." (PMID 25923732, 2015). "eIF4E expression predicted inferior EFS both in patients with GCB (p-value = 0.16) or ABC (p-value = 0.22) tumor subtypes." (PMID 25839159, 2015). "Additional downstream targets for mTOR include p70S6kinase and eukaryotic initiation factor-4E (eIF-4E), which are involved in modulating tumor cell metabolism, apoptosis, and autophagy." (PMID 25140303, 2014). "eIF4E, which is an element of the mammalian target of rapamycin (mTOR) pathway, has been considered an important target for ribavirin anti-tumor activity." (PMID 25904822, 2014). "In some malignancies, proteins lying downstream of the mTOR pathway have been also altered, for example, eIF4E, which promotes the phosphorylation of 4EBP1 (p-4EBP1), expression levels of which correlate with tumor progression." (PMID 24818169, 2014). "The systemic delivery of 4EASO (LY2275796) produced a knockdown in eIF4E, decreased malignancy-related proteins in a dose-dependent manner and prevented tumor growth in breast and prostate xenografts." (PMID 24260583, 2013). "Considerable evidence exists for therapeutic strategies that target eIF4E hyperactivation in preclinical models that result in inhibited tumor cell growth." (PMID 24260583, 2013). "In the majority of patients a decrease in eIF4E expression was observed when comparing pre- and post treatment tumor biopsies." (PMID 24260583, 2013). "Of these, 36 patients (55%) had elevated eIF4E in histologically tumor-free margins out of which 20 (56%) had local-regional recurrences." (PMID 22410369, 2012). "Conversely, U87MG cells in which Mnk1 had been knocked down by shRNA showed substantially reduced levels of phosphorylated eIF4E and markedly decreased tumour formation." (PMID 22392765, 2012).